KHDC3L (KH domain containing 3 like, subcortical maternal complex member)
Description:
Component of the subcortical maternal complex (SCMC), a multiprotein complex that plays a key role in early embryonic development (By similarity). The SCMC complex is a structural constituent of cytoplasmic lattices, which consist in fibrous structures found in the cytoplasm of oocytes and preimplantation embryos (By similarity). They are required to store maternal proteins critical for embryonic development, such as proteins that control epigenetic reprogramming of the preimplantation embryo, and prevent their degradation or activation (By similarity). KHDC3 ensures proper spindle assembly by regulating the localization of AURKA via RHOA signaling and of PLK1 via a RHOA-independent process (By similarity). Required for the localization of MAD2L1 to kinetochores to enable spindle assembly checkpoint function (By similarity). As part of the OOEP-KHDC3 scaffold, recruits BLM and TRIM25 to DNA replication forks, thereby promoting the ubiquitination of BLM by TRIM25, enhancing BLM retainment at replication forks and therefore promoting stalled replication fork restart (By similarity). Regulates homologous recombination-mediated DNA repair via recruitment of RAD51 to sites of DNA double-strand breaks, and sustainment of PARP1 activity, which in turn modulates downstream ATM or ATR activation. Activation of ATM or ATR in response to DNA double-strand breaks may be cell-type specific (By similarity). Its role in DNA double-strand break repair is independent of its role in restarting stalled replication forks (By similarity). Promotes neural stem cell neurogenesis and neuronal differentiation in the hippocampus (By similarity). May regulate normal development of learning, memory and anxiety (By similarity). Capable of binding RNA (By similarity).
Synonyms: C6orf221; ECAT1; HYDM2
Tractability: No criterion of Open Targets' tractability assessment is met for any kind of drug.
Gene: Protein-coding gene on chromosome 6 (73,362,658 to 73,364,171, forward strand). Ensembl gene ENSG00000203908.
Subcellular location: Cytoplasm; Cytoplasm, cell cortex; Nucleus; Mitochondrion; Cytoplasm, cytoskeleton, microtubule organizing center, centrosome; Chromosome
Gene Ontology:
Molecular function: protein binding; structural constituent of cytoplasmic lattice; RNA binding
Biological process: positive regulation of double-strand break repair via homologous recombination; regulation of protein localization; actin filament organization; establishment of organelle localization; establishment of spindle localization; negative regulation of apoptotic process; positive regulation of dendrite development; positive regulation of double-strand break repair; positive regulation of embryonic development; positive regulation of neurogenesis; protein storage; replication fork processing
Cellular component: chromosome; cytoplasm; nucleus; protein-containing complex; subcortical maternal complex; cell cortex; centrosome; cytoplasmic lattice; mitochondrion
Genetic constraint (gnomAD): Loss-of-function variants: 6 observed, 12.34 expected, observed/expected ratio (o/e) 0.49, 90% interval 0.26 to 0.96. The upper end of that interval is the gene's LOEUF score, 0.96, which puts it in group 4 of 6, group 1 being the genes least tolerant of losing a copy. Missense variants: 293 observed, 302.03 expected, observed/expected ratio (o/e) 0.97, 90% interval 0.88 to 1.07. Synonymous variants: 127 observed, 127.14 expected, observed/expected ratio (o/e) 1, 90% interval 0.86 to 1.16.
Homologues: Orthologues: chimpanzee KHDC3L (99% identical), macaque KHDC3L (88% identical), rat Khdc3 (39% identical), mouse Khdc3 (37% identical). Paralogues in human: OOEP (18% identical).
Diseases named in the same sentence as KHDC3L in open-access papers:
KHDC3L is named in the same sentence as 13 diseases in open-access papers, as found by Europe PMC text mining. Sharing a sentence is not in itself a finding about the gene and the disease. The quoted sentences say what the papers report.
hydatidiform mole (12 papers, 2015 to 2025). A gestational trophoblastic disorder characterized by marked enlargement of the chorionic villi, hyperplasia of the villous trophoblastic cells and hydropic changes. "To date, different variants have been reported in KHDC3L in cases of early pregnancy loss and hydatidiform moles." (PMID 36360157, 2022). "Rare biallelic variants of maternal KHDC3L have been reported to be associated with recurrent hydatidiform mole." (PMID 34925444, 2021). "It has been recently demonstrated that KHDC3L that is associated with recurrent hydatidiform mole is necessary for de novo methylation in human oocytes." (PMID 32928291, 2020). "Homozygous or compound-homozygous variants in the KHDC3L gene are the main cause of a biparental complete hydatidiform mole (BiCHM, a recurrent familial hydatidiform mole), a rare gestational abnormality, characterized by trophoblast overgrowth and the absence of embryo development." (PMID 36360157, 2022). "Biallelic mutations of maternal KHDC3L cause familial biparental hydatidiform mole." (PMID 31609975, 2019). "Thus, maternal and zygotic KHDC3L proteins may function differentially and their deficiencies contribute to distinct types of developmental failure, i.e., familial complete hydatidiform mole and common RPL, respectively." (PMID 31609975, 2019). "Mutations in two other members of the SCMC complex, NLRP7 and KHDC3L, contribute to 60% of the clinically recurrent hydatidiform moles." (PMID 37712067, 2023). "The pathogenesis of familial, biparental hydatidiform moles is caused by the inactivating mutations of NLRP7 and KHDC3L, genes involved in imprinting and inflammation." (PMID 31658584, 2019). "Pathological variants of zinc finger protein genes such as ZFP57 and ZNF445 and of genes related to the subcortical maternal complex such as NLRP2, NLRP5, NLRP7, and KHDC3L have been identified in cases of multilocus imprinting disturbances (MLIDs) and recurrent hydatidiform moles (RHMs)." (PMID 35581658, 2022). "Absence of maternal imprinting of gene expression in hydatidiform moles has also been observed in the rare biparental hydatidiform moles due to NLRP7 (NLR family pyrin domain containing 7) or KHDC3L (KH domain containing 3 like) mutations, suggesting a common endpoint of pathogenesis." (PMID 31658584, 2019). "The patients studied had a history of at least two episodes of a hydatidiform mole, and the impact of the NLRP7 and KHDC3L genes was clarified." (PMID 41011032, 2025).
mole (2 papers, 2023 to 2025). "The gestational history in conjunction with the diagnosis of the type of mole can direct the management towards testing for mutations in NLRP7 or KHDC3L genes." (PMID 38137915, 2023). "Molecular genotyping can be helpful in differentiating between androgenetic and biparental complete mole, and also in identifying germline mutations in NLRP7 and KHDC3L genes, responsible for recurrent mole." (PMID 40361748, 2025).
Adrenal insufficiency (1 paper, 2020). Insufficient production of steroid hormones (primarily cortisol) by the adrenal glands. "Among these were the associations of KHDC3L with ovarian insufficiency, RFX6 with diarrheal-type intestinal dysfunction, CYP11A1 (also known as cholesterol side chain cleavage enzyme) with adrenal insufficiency (AI), and SOX10 with vitiligo." (PMID 32410729, 2020).
Autoimmunity (1 paper, 2020). The occurrence of an immune reaction against the organism's own cells or tissues. "Using detailed clinical phenotyping, we find novel associations between autoantibodies and organ-restricted autoimmunity, including a link between anti-KHDC3L autoantibodies and premature ovarian insufficiency, and between anti-RFX6 autoantibodies and diarrheal-type intestinal dysfunction." (PMID 32410729, 2020).
female infertility (1 paper, 2022). Diminished or absent ability of a female to achieve conception. "Several studies have demonstrated that mutations in SCMC‐related genes (TLE6, PADI6, NLRP2, NLRP5, and KHDC3L) cause human female infertility in the form of an exhibition of EEA and fragmentation." (PMID 35946397, 2022).
Infertility (1 paper, 2020). "Furthermore, knockout of the NLRP5 and KHDC3L in female mice results in fertility defects, and human genetic mutations in these genes of the SCMC have been linked to infertility and molar pregnancies." (PMID 32410729, 2020).
ovarian insufficiency (1 paper, 2020). "The detection of anti-NLRP5 antibodies in a small subset of patients with non-APS1 ovarian insufficiency in a previous study further underlines the importance of evaluating the prevalence of anti-KHDC3L antibodies in women with POI." (PMID 32410729, 2020). "Our finding that females with APS1-associated ovarian insufficiency exhibit autoantibodies to KHDC3L, an oocyte specific protein, supports this hypothesis." (PMID 32410729, 2020). "We therefore chose to further investigate the relationship between anti-KHDC3L antibodies and ovarian insufficiency in our cohort." (PMID 32410729, 2020). "Finally, all 10 females in the expanded APS1 cohort with diagnosed ovarian insufficiency were also positive for anti-KHDC3L antibodies." (PMID 32410729, 2020). "Interestingly, a set of 5 proteins (KHDC3L, SRSF8, PNO1, RASIP1, and MORC2) exhibited a significant association with ovarian insufficiency in this cohort." (PMID 32410729, 2020). "Anti-KHDC3L PhIP-Seq enrichments are significantly different between APS1 patients with and without ovarian insufficiency." (PMID 32410729, 2020).
teratoma (1 paper, 2019). A non-seminomatous germ cell tumor characterized by the presence of various tissues which correspond to the different germinal layers (endoderm, mesoderm, and ectoderm). "Moreover, KHDC3L absence or mutations compromised the teratoma formation and decreased the teratomas size by triggering apoptosis." (PMID 31609975, 2019).
KHDC3L also shares sentences with these, for which no sentence is quoted: complete moles (1 paper); Miscarriage (1); Premature ovarian insufficiency (1); tumor (1); vitiligo (1).